Y_RNA (Y RNA )
Gene: Miscellaneous RNA gene on chromosome 16 (66,550,457 to 66,550,567, forward strand). Ensembl gene ENSG00000275745.
Homologues: Orthologues: chimpanzee Y_RNA (95% identical), dog Y_RNA (72% identical). Paralogues in human: RNY1 (76% identical), RNY1P11 (73% identical), Y_RNA (73% identical), Y_RNA (72% identical), Y_RNA (71% identical), Y_RNA (70% identical), Y_RNA (69% identical), RNY1P12 (68% identical), RNY1P8 (68% identical), Y_RNA (68% identical), RNY1P15 (68% identical), RNY1P10 (67% identical), and 86 more.